MAB21L4 (mab-21 like 4)
Synonyms: C2orf54; FLJ22671
Tractability: No criterion of Open Targets' tractability assessment is met for any kind of drug.
Gene: Protein-coding gene on chromosome 2 (240,886,048 to 240,896,893, reverse strand). Ensembl gene ENSG00000172478.
Subcellular location (Human Protein Atlas): Golgi apparatus; Nucleoplasm
Genetic constraint (gnomAD): Loss-of-function variants: 26 observed, 28.9 expected, observed/expected ratio (o/e) 0.9, 90% interval 0.66 to 1.25. The upper end of that interval is the gene's LOEUF score, 1.25, which puts it in group 5 of 6, group 1 being the genes least tolerant of losing a copy. Missense variants: 638 observed, 551.25 expected, observed/expected ratio (o/e) 1.16, 90% interval 1.08 to 1.24. Synonymous variants: 280 observed, 247.79 expected, observed/expected ratio (o/e) 1.13, 90% interval 1.02 to 1.25.
Homologues: Orthologues: chimpanzee MAB21L4 (99% identical), macaque MAB21L4 (95% identical), pig MAB21L4 (80% identical), dog MAB21L4 (79% identical), mouse Mab21l4 (77% identical), rat Mab21l4 (74% identical), guinea pig MAB21L4 (72% identical). Paralogues in human: MAB21L3 (18% identical), ITPRIP (15% identical), MAB21L2 (15% identical), MAB21L1 (14% identical), ITPRIPL1 (14% identical), ITPRIPL2 (14% identical), CGAS (13% identical), MB21D2 (12% identical), TMEM102 (9% identical).
Diseases named in the same sentence as MAB21L4 in open-access papers:
MAB21L4 is named in the same sentence as 3 diseases in open-access papers, as found by Europe PMC text mining. Sharing a sentence is not in itself a finding about the gene and the disease. The quoted sentences say what the papers report.
lung disorder (1 paper, 2021). A disease involving the lung. "Mab-21-like 4 (MAB21L4) has no known association with lung disorders or respiratory virus infections." (PMID 34376762, 2021).
MAB21L4 also shares sentences with these, for which no sentence is quoted: cancer (2 papers); tumor (2).